VEGFA (vascular endothelial growth factor A)
Diseases named in the same sentence as VEGFA in open-access papers (continued):
Sharing a sentence is not in itself a finding about the gene and the disease.
breast cancer (continued). "For example, ACE2 suppresses cell invasion and migration in NSCLC cells by suppressing VEGFA/VEGFR2/ERK pathway in breast cancer." (PMID 37521843, 2022). "CDK6 increases vascular endothelial growth factor A (VEGF-A) and c-Jun, promoting angiogenesis to allow the promotion of breast cancer progression and CDK4/6I resistance." (PMID 36358806, 2022). "Overall, endoglin controls and regulates DEHP-induced SIV sprouting and VEGFA expression in Tg (fli1: EGFP) embryos injected with breast cancer cells." (PMID 35203627, 2022). "Some past studies on cancer angiogenesis, in breast cancer cells and nude mice, also found miR-p16-5p to be a possible target of VEGFA." (PMID 35625769, 2022). "Previous studies have found that VEGFA was upregulated in various cancers, including non-small cell lung cancer, colorectal cancer, glioma, and breast cancer." (PMID 35681693, 2022). "The previous studies of CTECs in breast cancer mostly focused on monitoring treatment efficacy, especially antivascular endothelial growth factor-A (anti-VEGF-A) antibody bevacizumab." (PMID 36072971, 2022). "In mouse models of breast cancer, the adipose tissue sustains the growth of the new vasculature and supports the development and progression of the tumors via the secretion of VEGFA and other angiogenic factors." (PMID 36074318, 2022). "While knockdown of tRNAiMet led to downregulation of many proteins induced by tRNAiMet shRNA, quite unexpectedly, some proteins, including VEGFA, were upregulated in breast cancer HCC1806 cells in response to tRNAiMet knockdown." (PMID 35961977, 2022). "In breast cancer, non‐small cell lung cancer and acute myeloid leukaemia, the expression of VEGFA and Angpt2 increased simultaneously, which promoted tumour growth." (PMID 33987885, 2021). "We detected the expressed of angiogenesis-related factors in breast cancer cells and found that the mRNA levels of VEGFA and FGF2 were dramatically increased in PCDHB17P overexpression group." (PMID 34350110, 2021). "Hypoxia-induced upregulation of miR-191 was also demonstrated to enhance breast cancer cell proliferation, migration and survival by increasing levels of TGFß2 and downstream proteins including VEGFA both directly and indirectly." (PMID 33477629, 2021). "Down-regulation of MiR-20b can activate HIF-1α and VEGFA to promote breast cancer migration and invasion." (PMID 34857023, 2021). "NFIB is thus clinically relevant: it is preferentially expressed in the poor‐prognostic group of basal‐like breast cancers, and high expression of the NFIB/ERO1A/VEGFA pathway correlates with reduced breast cancer patient survival." (PMID 33751828, 2021). "A study found that the continuous activation of STAT3 and the overexpression of VEGFA occur with high frequency in breast cancer patients and contribute to chemoresistance and secondary malignancy." (PMID 34059068, 2021). "VEGFA is overexpressed in several types of cancer, including breast cancer, and plays a vital role in angiogenesis." (PMID 33747948, 2021). "Liang and colleagues found that hypoxia activated the HIF1α/VEGFA axis in breast cancer angiogenesis by inducing miR-153 expression and decreased expression of HIF1α and VEGFA, resulting in suppression of tumor angiogenesis." (PMID 34610581, 2021). "Activated NLRC4 leading to IL‐1β signalling has been reported to contribute to pathology and angiogenesis in obese mice with breast cancer via adipocyte‐mediated vascular endothelial growth factor A (VEGFA) expression." (PMID 33682108, 2021). "At the same time, hypoxia can induce MiR-153 to fine-tune HIF1α/VEGFA in breast cancer angiogenesis, MiR-100 can inhibit in vitro angiogenesis by regulating the mTOR/HIF-1α/VEGF signal transduction axis in breast cancer cells." (PMID 34857023, 2021). "In breast cancer, CAFs-derived tenascin C and VEGFA are the key molecules involved in metastasis to the lung." (PMID 34572878, 2021).
breast cancer (continued). "It was reported that ACE2 decreased the VEGFa expression of breast cancer cells, inhibiting phosphorylation of ERK1/2, suggesting that ERK signaling pathway mediated by ACE2 participated in the regulation of VEGFa." (PMID 34413267, 2021). "For instance, mesenchymal stem cells secrete exosomes containing miR-100 which inhibits angiogenesis by modulating the mTOR/HIF-1α/VEGFA signalling axis in breast cancer cells, thus reducing production of VEGFA by these cells." (PMID 33572413, 2021). "Many angiogenesis inhibitors have been approved by the FDA, however, only a few have been tested in breast cancer patients such as bevacizumab, which binds to VEGFA and blocks its efficacy." (PMID 33747948, 2021). "The heat map shows the significant correlations between ERO1 and PERK, EIF2 alpha, VEGFA, SERPINE1, PLAU, TFRC and MMP1 in basal tumors, confirming the strong association of ERO1 with the PERK branch of UPR and angiogenesis in basal breast cancer." (PMID 33531624, 2021). "Upregulation of VEGFA expression can promote the proliferation, angiogenesis and metastasis of gastric cancer cells and breast cancer cells." (PMID 34630524, 2021). "In most of the cell lines representative of aggressive ccRCC and breast cancers, VEGFA and NRP1 are expressed at high levels especially in the cell lines used in our respective experimental tumor growth (786-O and MDAMB231)." (PMID 33461580, 2021). "The antiangiogenic drug bevacizumab, a monoclonal antibody targeting VEGFA, has been proven to be less effective in treating breast cancer as a single agent." (PMID 34059068, 2021). "In particular, it was demonstrated that VEGFA expression is increased by hexachlorobenzene favoring angiogenesis in breast cancer models." (PMID 34444445, 2021). "For example, overexpression of EFEMP1 eliminated tumor development and suppressed angiogenesis and VEGFA expression in hepatocellular carcinoma, gastric and prostate cancers, and glioblastoma, while the converse was true with ovarian and breast cancers." (PMID 34069906, 2021). "Treatment of MCF-7 and MDA-MB-231 breast cancer cells with leptin led to increased expression of VEGFA." (PMID 32318345, 2020). "Recently, on the basis of the GEO database, Gu and his colleagues constructed an ARG model consisting of eight genes (BCL2, BIRC5, EIF4EBP1, ERO1L, FOS, GAPDH, ITPR1, and VEGFA), which can be used as an independent prognostic indicator of breast cancer." (PMID 32649310, 2020). "To establish a link between miRNA, HIF-1α, and the COX-2/EP4/PI3K/Akt pathway, we measured NFκB1, COX-2, EP4, and VEGFA gene expression in breast cancer cell lines, in both normoxia and hypoxia." (PMID 32707933, 2020). "Intriguingly, ezrin regulates the expression of angiogenic factors in both macrophages as well as tumor cells, as ezrin knockdown in breast cancer cells reduces the macrophage expression of VEGFA and MMP9 mRNAs." (PMID 33086476, 2020). "In breast cancer cells, overexpressing ci-miRNA-191, was associated with upregulated levels of TGF-β pathway genes (TGFβ2, SMAD3, BMP4, JUN, FOS, PTGS2, CTGF, and VEGFA), thus promoting breast cancer growth and metastasis." (PMID 32942528, 2020). "The NLRC4 inflammasome mediates the expression of adipocyte-mediated vascular endothelial growth factor A and angiogenesis, which accelerates the progression of breast cancer." (PMID 32397236, 2020). "We previously reported that increased expression of Zeb1 in breast cancer cells induces VEGFA production, thus promoting tumor angiogenesis and propagation." (PMID 33046710, 2020). "In contrast, VEGFA rs833061 demonstrated strong prognostic value in advanced colorectal cancer patients and, to a lesser extent, in breast cancer patients." (PMID 33238394, 2020). "In contrast, VEGFA expression was downregulated in monocytes of breast cancer and melanoma patients." (PMID 33042791, 2020).
breast cancer (continued). "Efficient RNAi-mediated down-regulation of GFP and VEGFA gene expression was achieved in MDA-MB-231-GFP+ breast cancer and EA.hy926 endothelial cells, respectively, by means of RGD1/siRNA polyplexes." (PMID 33050526, 2020). "ACE2 also down-regulates VEGFa expression in breast cancer cells and inactivates phosphorylation of VEGFR2, MEK1/2 and ERK1/2 in human umbilical endothelial cells, furthermore, ACE2 can prevent breast cancer cell metastasis in zebrafish models." (PMID 32339157, 2020). "The activities of the candidate molecules on regulating SerRS and VEGFA expression were first tested in breast cancer cells." (PMID 32550907, 2020). "VEGFA is upregulated in a variety of cancers such as in osteosarcoma, breast cancer, and bladder cancer." (PMID 32983957, 2020). "In breast cancer cells, miR-126 targets VEGFA and PIK3R2 to reduce VEGF/PI3K/AKT signaling and inhibit tumor angiogenesis." (PMID 32993787, 2020). "VEGFA is a potent regulator of angiogenesis and thereby involved in the development and progression of solid tumors, such as breast cancer." (PMID 33114046, 2020). "In our study, ACE2 inhibited the phosphorylation of VEGFR2, MEK1/2, and ERK1/2 in HUVECs through the downregulation of VEGFa in breast cancer cells." (PMID 31023337, 2019). "Gene MMP-9 and VEGFA play a critical and dual role in cancer metastasis and angiogenesis to foster progression of breast cancer cells in vitro." (PMID 30728391, 2019). "Firstly, we investigated the relationship between the combined expression of HMGA1 and FOXM1 with the VEGFA expression in breast cancer patients." (PMID 31311575, 2019). "Further qPCR and Western blotting results concordantly showed that ACE2 downregulated VEGFa expression in breast cancer cells, similar to the previous results in NSCLC." (PMID 31023337, 2019). "Compared with adjacent normal tissues, miR-29b expression is downregulated in breast cancer and endometrial carcinoma tissues, whereas VEGFA, ERK, and AKT3 are upregulated." (PMID 31757094, 2019). "The levels of several TGFβ pathway genes, including TGFβ2, SMAD3, BMP4, JUN, FOS, PTGS2, CTGF, and VEGFA, were found to be higher in miR-191-overexpressing breast cancer cells." (PMID 31590453, 2019). "This revealed that ERK signalling played a role in the process through which ACE2 downregulated VEGFa expression in breast cancer cells." (PMID 31023337, 2019). "Relationship between MIF, VEGFA expression level, and clinico-pathologic parameters of breast cancer by tissue microarray." (PMID 31293831, 2019). "In this respect, we have previously demonstrated that VEGFA and IL-6 cooperate in inducing the migration of breast cancer cells." (PMID 29707128, 2018). "More importantly, we recently reported that recombinant IL-6 cooperates with other factors, such as recombinant VEGFA, in sustaining breast cancer cell migration." (PMID 29707128, 2018). "A recent study indicated that VEGFA/neuropilin-1 pathway conferred cancer stemness via the activation of the Wnt/β-catenin axis in breast cancer cells." (PMID 29774034, 2018). "Analogously, the combination of anti-VEGFA and anti-IL-6 blocking antibodies was more efficient in inhibiting the spontaneous migration of breast cancer cells as compared with a single antibody." (PMID 29707128, 2018). "In fact, both VEGFA and IL-6 were able to significantly increase the ability to migrate of different breast cancer cell lines, with the combination of the two factors showing a greater effect as compared to treatment with a single protein." (PMID 29707128, 2018). "A similar analysis showed VEGFA expression was of greater prognostic importance in breast cancers defined as ER-negative by clinical ER protein immunohistochemistry (n=170 with both VEGFA and ER data)." (PMID 28504716, 2017). "MiR-29a and miR-29b were reported to target VEGFA in gastric cancer and breast cancer, respectively." (PMID 28241836, 2017).
breast cancer (continued). "For example, breast cancer cell networks upregulated VEGFA fold change = 1.65 and MMP14 fold change = 1.72, but fibrosarcoma cell networks did not." (PMID 29162797, 2017). "We have identified previously that vascular-endothelial growth factor-A (VEGF-A) interacts with sensory neurons and is known to be upregulated in breast cancer." (PMID 29100335, 2017). "Among aggressive breast cancers expressing high VEGFA, those with SOX2 overexpression define an even more aggressive subgroup in the two independent data sets evaluated." (PMID 28504716, 2017). "The pathway linking VEGFA to Sox2 upregulation, miR-452 loss and SNAI2 induction is supported by our analysis of two major data sets including over 2500 primary human breast cancers." (PMID 28504716, 2017). "Expression of these VEGFA isoforms has been observed in several cancer types including breast cancer." (PMID 28008154, 2017). "Correspondingly, we demonstrate that CITED2 regulates VEGFA expression in breast cancer cells, at least in part via modulation of TGF-β-induced transcription." (PMID 28008154, 2017). "Some of these polymorphisms (-2578C>A, -1154G>A, -634G/C and +936C/T) have been related to varying VEGF protein expression and serum VEGFA levels, in various diseases, such as renal cell carcinomas, recurrent pregnancy loss, breast cancer and lung cancer." (PMID 29682488, 2017). "Stepwise investigation demonstrated miR-29c directly bound to the 3′-UTR region of VEGFA, and reduced VEGFA protein expression in breast carcinoma cells, coupled with the downregulation of HIF-α." (PMID 29069797, 2017). "Analysis using the Oncomine research tool revealed that mRNA levels of Fibronectin (FN1) and VEGFA are significantly elevated in the tumor and stromal compartments of breast carcinomas." (PMID 28977919, 2017). "Stepwise investigation from in vitro and in vivo experiments demonstrated that miR-16-5p overexpression suppressed tumor growth and reduced HIF-α and VEGFA expressions in breast carcinoma cells and nude mice tumor tissues." (PMID 29069797, 2017). "In this study, we showed that ectopic expression of ZEB1 resulted in significant upregulation of VEGFA synthesis in MDA-MB-231 breast cancer cells, thus promoting tumor angiogenesis in vitro and in vivo." (PMID 26882471, 2016). "Here, using chemoresistant breast cancer cell models, we show that miR-205 targets VEGFA as well as FGF2 mRNA 3′-UTR and represses their expression, leading to impaired PI3K/AKT signaling and increased apoptosis both in vitro and in vivo." (PMID 27362808, 2016). "Taken together, these observations suggest that ZEB1-expressing breast cancer cells have elevated VEGFA production and thus stimulate tumor angiogenesis via a paracrine mechanism." (PMID 26882471, 2016). "On the basis of these results, we propose a model in which elevated expression of ZEB1 in breast cancer cells activates the secretion of VEGFA protein and creates a chemotactic gradient to promote angiogenic stimulation." (PMID 26882471, 2016). "Collectively, these data suggest that the loss of miR-205 induces VEGFA/FGF2 expression, thus conferring chemoresistance in breast cancer." (PMID 27362808, 2016). "Another target for treatment of breast cancer and many other tumor types is vascular endothelial growth factor A (VEGF-A), which is involved in tumor angiogenesis." (PMID 27252651, 2016). "Collectively, we found that ZEB1-expressing breast cancer cells increase VEGFA production and thus stimulate tumor growth and angiogenesis via a paracrine mechanism." (PMID 26882471, 2016). "Taken together, our data suggest that miR-205 enhances chemosensitivity of breast cancer cells to TAC chemotherapy by suppressing both VEGFA and FGF2, leading to evasion of apoptosis." (PMID 27362808, 2016). "The authors show that ZEB1 overexpression in breast cancer cells recruits Sp1 to VEGFA promoter region and activates VEGFA expression and secretion, therefore promoting angiogenesis in vitro and in vivo." (PMID 27411336, 2016).
breast cancer (continued). "It remains to be determined if VEGFA and its receptor VEGFR2 and VEGFC and its receptor VEGFR3, and CSF2 and its receptor GMRA/GMRB can also serve as therapeutic targets for HER2+ breast cancer since the associations we found were modest." (PMID 26173622, 2015). "We found that VEGFa mRNA expression is 5 and 3 fold lower in K1 and K2 Ncoa1 knockout mouse mammary tumor cells than that in W1 and W2 Ncoa1 WT mouse mammary tumor cells, respectively." (PMID 26287601, 2015). "Knockdown of NCOA1 using two different shRNAs in MDA-MB-231 human breast cancer cells also drastically reduced both VEGFa mRNA expression and VEGFa protein secreted into the culture medium." (PMID 26287601, 2015). "First, we showed that the compromised ability of Ncoa1 null mammary tumor cells to induce in vivo angiogenesis can be rescued by VEGFa treatment, suggesting a reduced secretion of VEGFa from Ncoa1 null cells." (PMID 26287601, 2015). "In TCGA data, VEGFA expression is highest in HER2+ breast cancer (p-value of 5 × 10−3 relative to other subtypes)." (PMID 26173622, 2015). "Together, the consensus of these results indicates that VEGFa expression levels positively correlate with Ncoa1 expression levels in multiple breast cancer mouse models." (PMID 26287601, 2015). "NCOA1 works not only with both HIF1α and AP-1 to upregulate VEGFa expression as shown in this study but also works with different transcription factors to upregulate different target genes to promote breast cancer progression and metastasis." (PMID 26287601, 2015). "Angiogenesis within the brain has been shown to depend on the vascular endothelial growth factor A (VEGF-A) in melanoma as well as lung, colon, and breast carcinoma models." (PMID 26667022, 2015). "A recent study describing a role for ARRB1 in HIF1A-dependent VEGFA expression in breast cancer cells supports our findings." (PMID 24837709, 2014). "Overexpression of MT1-MMP in the breast cancer cell line MCF-7 increased transcription of vascular endothelial growth factor A (VEGF-A) and, concurrently, tumor growth, angiogenesis, and metastasis." (PMID 24549119, 2014). "In the group of breast cancer patients, VEGFA initially increased in all patients and declined back on day 7, except for one outlier with locally advanced disease (T2N2) who eventually relapsed." (PMID 23981902, 2013). "In the cohort of breast cancer patients, VEGFA increased on day 3 (P = 0.038) and declined on day 7 (P= 0.017), while IL8 did not change on day 3 but showed a significant decline on day 7 (P = 0.02)." (PMID 23981902, 2013). "DRBP76 also binds the VEGFA HSR in hypoxic breast cancer cells, increasing mRNA stability and translation, but the binding region within the VEGFA HSR in these experiments was not determined." (PMID 23976881, 2013). "Postoperatively, a transient increase in circulating levels of VEGFA was documented for nearly all patients who underwent surgery for breast cancer 3 days after surgery which waned back 4 days later." (PMID 23981902, 2013). "The combination of interleukin-6 (IL-6) and vascular endothelial growth factor A (VEGF) secreted from mesenchymal stem cells increases the ability of breast cancer cell lines to migrate." (PMID 24147217, 2013). "Tissue microarray of 642 breast cancers demonstrated that high levels of VEGFA and its receptors- VEGFR-1, VEGFR-2, and NRP-1 were significantly associated with poor survival." (PMID 23203097, 2012). "Incorporation of bevacizumab, a humanized monoclonal antibody to VEGFA, in chemotherapy, is one of the rapidly evolving areas in the treatment of breast cancer." (PMID 23203097, 2012). "Although crosstalk can occur between DDT signaling estrogen response elements, as previously shown, the results presented here strongly suggest that DDT-altered VEGFA expression in MCF-7 breast cancer cells is ERα independent." (PMID 22609851, 2012).